CETP (cholesteryl ester transfer protein)
Diseases named in the same sentence as CETP in open-access papers (continued):
Sharing a sentence is not in itself a finding about the gene and the disease.
dyslipidemia (126 papers, 2007 to 2026). "The selective cholesteryl ester transfer protein (CETP) inhibitor obicetrapib is in clinical evaluation for dyslipidemia and cardiovascular risk reduction." (PMID 41887531, 2026). "While we acknowledge the limitations associated with our current study, E3L.CETP mice on a chow diet provide an unique tool to study mechanisms of sex-dependent pathogenesis of dyslipidemia-accelerated vascular ageing." (PMID 40240752, 2025). "From a genetic perspective, although the CETP polymorphism demonstrated significant genotype distribution differences between the dyslipidemia and non-dyslipidemia groups, its independent influence in the adjusted model was not statistically significant." (PMID 40428368, 2025). "Adult MetS is inversely associated with the presence of the Taq-1B (rs708272) allele which, by reducing CETP expression, protects from dyslipidemia." (PMID 38133765, 2024). "Obicetrapib is an oral, once-daily, low-dose, safe, and tolerable CETP inhibitor under development for the treatment of dyslipidemia, CVD risk, and Alzheimer’s disease." (PMID 38786974, 2024). "In a Korean cohort, the CETP variant rs9926440 showed a strong correlation with chronic conditions such as MetS and dyslipidemia." (PMID 39765884, 2024). "This highlights the fact that hypoalphalipoproteinemia is the main dyslipidemia detected in the Mexican population, partly as a consequence of the high prevalence of polymorphisms in the CETP, APOA1, and ABCA1 genes." (PMID 37892400, 2023). "The main research topics during this period were focused on reducing atherosclerotic risk, pharmacology clinical trials, cardiovascular risk, raising HDL-C, lipoprotein testing, cholesteryl ester transfer protein, and metabolic syndrome, among others." (PMID 38017531, 2023). "In this regard, it has been proposed that the B1 allele has been linked with the risk of dyslipidemia due to the linkage with further CETP activity and increased TG." (PMID 37407953, 2023). "Anacetrapib is a novel cholesteryl ester transfer protein (CETP) inhibitor designed for cardiovascular risk reduction and the treatment of hypercholesterolemia and mixed dyslipidemia." (PMID 29353335, 2018). "We previously demonstrated that five of the eight functional CETP polymorphisms (rs1800775, rs3764261, rs12149545, rs711752, and rs708272) are closely linked to dyslipidemia among the Uyghur and Kazakh populations." (PMID 28629169, 2017). "As such, factors other than this mutation in CETP must play an important role in the pathogenesis of dyslipidemia associated with AMD." (PMID 28698208, 2017). "In this study, of the CETP gene eight SNPs we confirmed that at five genetic loci were associated with lipid parameters or dyslipidemia in a Uyghur and Kazakh national minority population in Xinjiang." (PMID 26694435, 2015). "The CETP gene has been identified as an important independent risk factor of dyslipidemia and has become a hot research spot, and several mutations in this gene have been reported." (PMID 26694435, 2015). "We found that in our study group eight SNPs located in the CETP gene, were the most associated with dyslipidemia." (PMID 26694435, 2015). "Association of CETP SNPs in Dyslipidemia and Normal Control individuals in Xinjiang national minority." (PMID 26694435, 2015). "We have investigated the relationship between the polymorphisms and haplotypes in the CETP gene, and dyslipidemia among the Xinjiang Kazak and Uyghur populations in China." (PMID 26694435, 2015). "Our study is also on a single gene, CETP, so further evaluation of the tSNPs among multiple genes and loci set of cases and controls is needed in the future in order to better clarify dyslipidemia associations with gene polymorphism." (PMID 26694435, 2015). "As the first study of the association between the CETP multiple loci and dyslipidemia in Western China, we investigated the possible pathogenesis of dyslipidemia from a genetic perspective." (PMID 26694435, 2015).
dyslipidemia (continued). "Higher CETP activity has been shown to be closely associated with hepatic steatosis in patients with metabolic syndrome." (PMID 25486007, 2014). "Previous studies have also shown an association between this polymorphism and the metabolic syndrome, independently of the well-known effect on HDLc concentrations and insulin resistance, a fact that suggests a possible role of CETP on glucose metabolism." (PMID 22073289, 2011). "While CETP variants may contribute to lipid metabolism, their specific role in dyslipidemia remains uncertain, warranting further investigation in larger, multiethnic cohorts." (PMID 40428368, 2025). "Moreover, they identified another CETP polymorphism, A373P (rs5880), which increases the risk of dyslipidemia and related cardiovascular complications." (PMID 38133765, 2024). "Thus, fat mass and obesity-associated or cholesteryl ester transfer protein gene polymorphisms have been correlated with obesity and dyslipidemia, thus contributing to the escalation of pediatric MetS incidence." (PMID 39723164, 2024). "CETP was also involved in dyslipidemia-related susceptibility to cognitive decline." (PMID 36192674, 2022). "In spite of high HDL-C levels, we speculate that these certain number of subjects with CETP deficiency had increased risk of dyslipidemia." (PMID 28927404, 2017). "However, the relationship between CETP gene polymorphism and dyslipidemia is very complex, and CETP gene is influenced by environmental factors and metabolic factors in the process of lipid abnormality." (PMID 26694435, 2015). "A total of 712 patients with dyslipidemia and 764 control subjects of CETP gene polymorphism at rs12149545, rs3764261, rs1800775, rs711752, rs708272, rs289714, rs5882, and rs1801706 loci were studied by the Snapshot method, linkage disequilibrium analysis and haplotype construction." (PMID 26694435, 2015). "Frequently associated with metabolic syndrome and type 2 diabetes mellitus, this phenotype is pathophysiologically linked to hepatic overproduction of ApoB-containing lipoproteins, delayed lipolysis, and increased cholesteryl ester transfer protein (CETP)-mediated lipid exchange." (PMID 41346943, 2025). "Furthermore, a strong correlation was found with increase homozygosity for the 405V variant in CETP (cholesteryl ester transfer protein) in centenarians, also associated with a unique lipoprotein phenotype and lower prevalence of metabolic syndrome and with preservation of cognitive function." (PMID 17784782, 2007). "HDL-C is a useful metric for the diagnosis of metabolic syndrome, and this is largely due to the known mechanism of net HDL particle loss via the process of cholesteryl-ester transfer protein-mediated remodeling in the context of high plasma TG." (PMID 40623654, 2025). "Early clinical trials demonstrated encouraging outcomes in patients with dyslipidemia treated with CETP inhibitors, but the development of these inhibitors encountered several disappointing challenges in later-stage trials." (PMID 40375946, 2025). "Suppressing the activity of cholesteryl ester transfer protein (CETP) is another cinnamon potential mechanism to improve dyslipidemia." (PMID 39021815, 2024). "Therefore, the CETP gene variants added to the intrinsic factors of hemolytic anemia itself (cumulative effect of chronic hemolysis, oxidative stress, and inflammation) could explain part of the variation observed in dyslipidemia in patients with SCD." (PMID 38265339, 2024). "Substantial advances in understanding the genetic basis of dyslipidemia have recently suggested that the cholesteryl ester transfer protein (CETP) is involved in the pathogenesis of CAD." (PMID 38146445, 2023). "Considering that the elevated CETP activity is a major determinant of the atherogenic dyslipidemia, i.e., pro-atherogenic reductions in HDL and LDL particle size, inhibition of CETP emerged as a promising pharmacological target during the past two decades." (PMID 36881278, 2023).
dyslipidemia (continued). "Its mechanism of action is possibly related to the inflammatory alterations and dyslipidemia induced by increased expression of CETP and PLTP in mice with psoriasis." (PMID 35982498, 2022). "For instance, ZPR1 and BUD13 were well-documented for lipid level, HERPUD1 was found related to HDL-C in the Korean population, and the APOA5 and CETP also showed evidence of contributing to triglycerides, metabolic syndrome, and HDL-C." (PMID 35238325, 2022). "In the current study, we concentrated on plasma triglyceride in combination with obesity and used MINGLeD to analyse which processes are altered during the progression of the metabolic syndrome in male APOE*3-Leiden.CETP mice on a high-fat diet." (PMID 36432620, 2022). "Conceptualizing of CETP in this way helps explain the profile of individuals with atherogenic dyslipidemia, typified by high serum TG, low HDL-C, and a preponderance of small dense LDL particles (sdLDLs)." (PMID 35629964, 2022). "Ongoing or future dyslipidemia trials involving CETP inhibition would therefore benefit from studying its HDL-bound metabolic properties." (PMID 33351780, 2021). "Altogether these data show that in lean E3L.CETP mice, rimonabant attenuates dyslipidemia, induces a shift from glucose to FA oxidation, and stimulates WAT browning." (PMID 33766515, 2021). "The E3L.CETP mouse is a promising translational model for studying diet‐induced obesity and metabolic syndrome." (PMID 33932122, 2021). "Among these potential candidate genes, there are six genes (CETP, APOB, TMEM258, FADS2, FADS1, and PVRL2) associated with all phenotypes of dyslipidemia." (PMID 32425817, 2020). "CKD-519 is a selective and potent cholesteryl ester transfer protein (CETP) inhibitor that is being developed for dyslipidemia." (PMID 32575566, 2020). "Many genetic variants involved in the pathogenesis of the metabolic syndrome had been found to be associated with lipid metabolism, namely, SNPs in the APOA5, APOC3, and CETP genes." (PMID 29666642, 2018). "Elevated levels of CETP activity was found to be a major determinant of the atherogenic dyslipidemia, and atherosclerotic cardiovascular disease." (PMID 30072955, 2018). "The aim of the present trial was to evaluate the effect of curcumin and its modified formulation on serum CETP concentrations in patients with metabolic syndrome." (PMID 30377591, 2018). "Although our study didn’t incorporate all of the CETP gene locus this study suggests that several loci in the Uyghur and Kazak populations are clearly related to dyslipidemia." (PMID 26694435, 2015). "We performed a meta-analysis of all published randomized controlled trials by using CETP inhibitors as a mono-therapy or co-administered with statins versus placebo for treating patients with dyslipidemia." (PMID 24204732, 2013). "There are some early clinical trials showing the inspiring results of CETP inhibitors in the treatment of patients with dyslipidemia." (PMID 24204732, 2013). "We performed a meta-analysis study to determine the efficacy and safety of CETP inhibitors in treating patients with dyslipidemia." (PMID 24204732, 2013). "In conclusion, CETP inhibitors exert excellent effects on the lipid parameters in patients with dyslipidemia even in combination with statin therapy." (PMID 24204732, 2013). "As most of the treatment durations of the enrolled studies are relatively short (4–12 weeks), we mainly focused on the lipid modifying efficacy and safety of CETP inhibitors in patients with dyslipidemia." (PMID 24204732, 2013). "In clinical trials, inhibition of CETP with SMIs significantly lowered plasma TG, and administration of torcetrapib in patients with combined dyslipidemias displayed enhanced postprandial VLDL-TG metabolism." (PMID 23801661, 2013). "CETP plays an important role in the regulation of HDL metabolism and is shown to be associated with dyslipidemia in GWA studies." (PMID 20122255, 2010).
dyslipidemia (continued). "Found dyslipidemia to be associated with higher BMI and altered lipid profiles; significant differences in CETP genotype distribution between groups, although CETP variants did not independently predict dyslipidemia risk." (PMID 40428368, 2025). "Despite identifying significant differences in CETP genotype distributions between participants with and without dyslipidemia, this study determined that these variants were not independent predictors after controlling for other clinical and metabolic factors." (PMID 40428368, 2025). "Critically, since CETP inhibitors such as obicetrapib are currently in phase 3 clinical trials to treat dyslipidemia and coronary artery disease, its clean safety and toxicity profile makes it a good repurposing candidate for metabolic disease and combination therapies." (PMID 37398493, 2023). "Indeed, inflammation and its cytokine-mediated changes in lipase activity (e.g., incretins, lipoprotein lipase, and cholesteryl ester transfer protein activity) potentially drive the alteration of atherogenic dyslipidemia." (PMID 36691001, 2023). "Obviously CETP concentration is increased in subjects with dyslipidemia." (PMID 35448527, 2022). "In animal model experiments conducted on 30 male rabbits with dyslipidemia, treated with 10-Dehydrogingerdione, a novel cholesteryl ester transfer protein (CETP) inhibitor, which is able to suppress PCSK9 expression, induced a marked decrease in the soluble sCD40L and sP-selectin." (PMID 35326219, 2022). "APOE*3-Leiden.CETP mice, as part of an inbred mouse model in which mice develop the metabolic syndrome upon being fed a high-fat high-cholesterol diet, show large inter-individual variation in the parameters of the metabolic syndrome, despite a lack of genetic and environmental variation." (PMID 36432620, 2022). "CKD-519 is a potent, selective CETP inhibitor being developed for the treatment of dyslipidemia." (PMID 32575566, 2020). "Even closer to the human profile are the Apoe*3-Leiden.CETP mice, which are certainly the model of choice to study human CETP but also changes in lipid profiles that are also observed in humans suffering from the metabolic syndrome." (PMID 31032262, 2019). "Therefore, CETP has become a target for the treatment of dyslipidemia, and CETP inhibitors are expected to be a powerful class of drugs for increasing HDL and decreasing LDL levels, which should help reduce the risk of atherosclerotic CVD." (PMID 31311144, 2019). "Moreover, future studies using an LPL agonist alone or in combination with a CETP inhibitor need to be conducted in order to investigate the possibility of LPL as a therapeutic target of dyslipidemia and CVD." (PMID 31234537, 2019). "Consequently, this study was conducted in order to compare the effect of curcumin and complex curcumin on CETP level among patients with metabolic syndrome." (PMID 30377591, 2018). "Interestingly, four of the top five significant genes (GALNT2, SNX17, CETP, LIPC) were regarded as dyslipidemia associated genes in the original GWAS study." (PMID 30110382, 2018). "Here, we study whether male E3L.CETP mice are an adequate model to study the metabolic syndrome in man, by following their response to a high‐fat high‐cholesterol diet (HFCD) for 6 months." (PMID 29038350, 2017). "Cholesteryl ester transfer protein (CETP) inhibitors are a new class of therapeutics for dyslipidemia that simultaneously improve two major cardiovascular disease (CVD) risk factors: elevated low-density lipoprotein (LDL) cholesterol and decreased high-density lipoprotein (HDL) cholesterol." (PMID 28911944, 2017). "At present, the study of the CETP gene is mainly related to dyslipidemia." (PMID 28629169, 2017).
dyslipidemia (continued). "CETP inhibitors therapy is associated with significant increase in HDL-c and decrease in triglyceride and LDL-c with satisfactory safety and tolerability in patients with dyslipidemia." (PMID 24204732, 2013). "CETP is an independent risk factor for CHD and metabolic syndrome." (PMID 22211242, 2012). "In addition, we recently reported that the metabolic syndrome in male patients is characterized by a 38% higher serum cholesteryl ester transfer protein (CETP) activity than the control group." (PMID 22211242, 2012). "However, logistic regression analysis did not support an independent effect of CETP genotypes on dyslipidemia risk." (PMID 40428368, 2025). "Taken together, the model’s moderate fit and its limited ability to explain variability reinforce the idea that, in the context of this particular model, the CETP AA and CA genotypic variables did not emerge as significant independent predictors of dyslipidemia risk." (PMID 40428368, 2025). "Furthermore, no research has been found on the relationship of dyslipidemia with CETP gene polymorphisms in this group." (PMID 38265339, 2024). "Therefore, although CETP is a known marker of dyslipidemia and its elevated concentrations are observed in such individuals, and although psoriatics are also in increased risk of this disorder, CETP status in such patients may not be easy to establish." (PMID 35448527, 2022). "Additionally, rs117026536 in the LPL gene, rs651821 in the APOA5 gene, rs9926440 in the CETP gene, and rs429358 in the APOE gene were associated with dyslipidemia.The GWAS analysis of the male subjects revealed 13 significant SNPs in the discovery stage (P < 5 × 10− 8)." (PMID 36419087, 2022). "The APOE*3-Leiden(E3L).CETP mouse is a mouse model for human MetS that develops diet-induced dyslipidemia and is prone to develop obesity and insulin resistance." (PMID 29879115, 2018). "However, whether E3L.CETP mice are a good model to study the development of metabolic syndrome through time is unclear to date." (PMID 29038350, 2017). "Thus, CETP inhibition could be a novel protective strategy for dyslipidemia related to diabetes and obese." (PMID 26973702, 2016). "Based on the adjustment of age, sex and body mass index, the risk degree was evaluated by dyslipidemia (0 = no, 1 = yes) as the dependent variable, and the main allele was the control, and the CETP gene was analyzed by single factor logistic regression analysis, OR and 95%CI." (PMID 26694435, 2015). "Our prior investigation into Cuban policosanol demonstrated its efficacy in improving hypertension and dyslipidemia by elevating HDL-C and inhibiting CETP." (PMID 38675370, 2024). "Of note, the other two SNPs, rs56156922 (CETP) and rs662799 (APOA5), appeared to be dyslipidemia-related SNPs found only in men." (PMID 36419087, 2022). "The third characteristic of atherogenic dyslipidemia (in addition to elevated TG and diminished HDL-C) is a preponderance of sdLDLs, which can also be framed by our discussion of CETP." (PMID 35629964, 2022). "Moreover, Apoe*3-Leiden.CETP mice fed a high-fat high-cholesterol diet for 6 months mimic changes in lipid profiles observed in humans suffering from the metabolic syndrome, and may therefore be the preferred model to study age-related changes in lipid metabolism and reverse cholesterol transport." (PMID 31032262, 2019). "While, it has been reported that inhibition of plasma CETP by apoC-I is blunted in CHD patients with dyslipidemia, this is probably due to increasing amounts of VLDL-bound apoC-I, which is inactive as a CETP inhibitor." (PMID 24859250, 2014). "Previous researches in our laboratory using experimental model of metabolic syndrome have shown that the introduction to animals of grape polyphenols complex inhibited LDL oxidation, HDL lipid peroxidation, normalized PON and CETP activity levels." (PMID 23936611, 2013).